IL1B (interleukin 1 beta)
Diseases named in the same sentence as IL1B in open-access papers (continued):
Sharing a sentence is not in itself a finding about the gene and the disease.
schizophrenia (continued). "The levels of both IKKβ and NIK transcripts, which were specifically lower in high inflammation schizophrenia, were also inversely correlated with IL-1β mRNA and plasma CRP levels in patients." (PMID 35027554, 2022). "Patients with a continuous course of schizophrenia showed statistically significantly greater levels of IL-12p70 (p = 0.019), IL-1α (p = 0.046), and IL-1β (p = 0.035) compared to patients with an episodic course." (PMID 36556337, 2022). "IL-1β is important in the cognition of patients with schizophrenia, as it is needed for long-term potentiation of synaptic transmission and seems to play a crucial role in hippocampal neurogenesis." (PMID 35887634, 2022). "In conclusion, the current study showed that TLR4/NF-κB/IL-1β signaling elevates in activity but responds sluggishly to LPS stimulation in schizophrenia." (PMID 36051545, 2022). "People with schizophrenia also had approximately 25% higher leukocyte IL-1β mRNA (Cohen’s d = 0.63) and 42% higher IFN-γ (Cohen’s d = 0.65) mRNA than controls (both p < 0.001, both adjusted p < 0.02)." (PMID 35027554, 2022). "In our study, patients with a continuous course of schizophrenia had elevated levels of proinflammatory cytokines (IL-12p70, IL-1α, and IL-1β) as compared with patients with an episodic course." (PMID 36556337, 2022). "The most interesting finding to emerge from all these analyses was indeed that genes involved in synaptic transmission respond differentially to IFNγ and IL-1β exposure in schizophrenia NPCs compared to control NPCs." (PMID 35716830, 2022). "Several studies have evaluated the levels of the IL-1 cytokines in schizophrenia, reporting increased levels of IL-1β and IL-1Ra in the plasma of schizophrenia patients, as well as decreased levels of IL-1α." (PMID 35163653, 2022). "In the present study, we recruited a relatively larger sample of patients with schizophrenia and measured more plasma inflammatory cytokines, including IL-1β, IL-2, IL-4, IL-6, IL-8, IL-10, IL-12, IL-17, TNF-α, IFN-γ, and CRP." (PMID 36341400, 2022). "We observed that genes upregulated in SZ NPCs treated with IL-1β showed a significant overlap with those upregulated in schizophrenia cases (p = 0.0013, FDR = 0.0052, odds ratio (OR) = 1.6)." (PMID 35716830, 2022). "Patients with a continuous course of schizophrenia showed statistically significantly higher levels of IL-12p70 (p = 0.019), IL-1α (p = 0.046), and IL-1β (p = 0.035) compared with patients with an episodic course." (PMID 36556337, 2022). "It has previously been shown that there is a positive association between IL-1β, IL-6, and TNF-α and prolactin levels in patients with schizophrenia." (PMID 35958655, 2022). "We found diagnostic increases in SERPINA3, TNFα, IL1β, IL6, and IL6ST transcripts in schizophrenia compared with controls (p < 0.02–0.001)." (PMID 31168068, 2021). "It is reported that schizophrenia patients with a first-episode psychosis were observed to have increased blood concentrations of IL-1β, IL-6, IL-12, IFN-ɣ, TNF-α, TGF-β and sIL-2R compared to healthy controls." (PMID 34589729, 2021). "Increased levels of the pro-inflammatory cytokines IL-6, IL-1β, and IL-8 has been observed in CSF obtained from patients with schizophrenia." (PMID 33976392, 2021). "An increased release of IL-1β by peripheral monocytes before treatment, and then normalization by antipsychotic medication, has been described in patients with schizophrenia." (PMID 33746786, 2021). "Schizophrenia has been attributed to a dysfunction of brain dopaminergic and glutamatergic circuits, and it is known that IL-1β can induce the conversion of rat mesencephalic progenitor cells into a dopaminergic phenotype." (PMID 33746786, 2021). "In schizophrenia, IL1B and SERPINA3 mRNAs positively correlated and P2RY12 mRNA negatively correlated with standardised lifetime antipsychotic dose (all p ≤ 0.022)." (PMID 34911938, 2021).
schizophrenia (continued). "Activation of TLR3 leading to an upregulation of IL-1β, CCL2, and CXCL10 are also seen in models of autism and schizophrenia associated with white matter abnormalities." (PMID 33558485, 2021). "Several studies have suggested that IL-1β plays an important role in the etiology and pathophysiology of schizophrenia." (PMID 33746786, 2021). "Risperidone therapy led to an increase in IFN-α2, IL-1β and IL-7 in schizophrenia patients with MetS." (PMID 34065135, 2021). "We have not looked forward and examined the signaling pathways activated by biomarker candidates of schizophrenia, such as tumor necrosis factor-alpha, IL-1β, and IL-6." (PMID 33402704, 2021). "Previous postmortem studies have consistently reported increased gene expression of IL1β in schizophrenia." (PMID 33815179, 2021). "IL-1B, IL6, and IL6R genes were associated with schizophrenia in a meta-analysis and an association study." (PMID 33315097, 2021). "Another study in patients with schizophrenia reported a positive correlation between plasma IL-1β and kynurenine levels." (PMID 34802039, 2021). "Activated inflammatory microglia release pro-inflammatory cytokines such as TNF-α, IL-1β, and IL-6 and the specific influence of these inflammatory cytokines on neurotransmitter systems reportedly leads to schizophrenia and other psychiatric disorders." (PMID 32341334, 2020). "A recent study compared TSPO PET of schizophrenia patients and controls with combined peripheral and CSF measures of IL1β, IFNγ, IL-10, IL-6 and TNF-α." (PMID 32179746, 2020). "These cytokines were selected to include those (IL-6, IL-1β, TNFα) that can be increased in the serum of patients with schizophrenia or autism spectrum disorders." (PMID 33288794, 2020). "We find ~38% of schizophrenia cases have a significant increase in mRNA levels of interleukin (IL)-1β, IL-6, IL-8 and SERPINA3 in both the dorsolateral prefrontal cortex (DLPFC) and the orbitofrontal cortex (OFC)." (PMID 30214039, 2020). "The exacerbated decrease in ABCG2 in the “high inflammation” schizophrenia subgroup is consistent with evidence showing that treatment with IL-1β, IL-6 and TNFα reduces both mRNA and protein expression of endothelial ABCG2 in vitro." (PMID 30214039, 2020). "It is also worth noting that many of the cytokines altered in the maternal serum are also elevated in the blood of patients with schizophrenia, including IL-1β, IL-2, IL-6, IL-12 and TNF-α." (PMID 30691477, 2019). "A meta-analysis including 16 studies comparing schizophrenia with healthy controls, found increased CSF levels of IL-1β, IL-6, IL-8, kynurenine, and kynurenic acid, while sIL-2R was decreased." (PMID 30766494, 2018). "How the interaction between TNF-α and IL-1β is participated in the pathogenesis of schizophrenia warrants the further investigation." (PMID 29867314, 2018). "Only one previous study reported a significant positive correlation between levels of TNF-α and IL-1β in schizophrenia patients." (PMID 29867314, 2018). "In comparison to controls, schizophrenia patients had higher levels of IL-2 (U = 1573.5, p < 0.001) and also the inflammatory cytokines IL-1β (U = 1565.5, p = 0.011), IL-6 (U = 1975.5, p = 0.018), and IFN-γ (U = 2076.0, p = 0.018)." (PMID 29803226, 2018). "In terms of clinical symptomatology, a significant positive relationship was identified between SAPS scores and IL-1β (rs = .367, p = 0.012) in the schizophrenia group." (PMID 29803226, 2018). "Recently, one study found that TNF-α and IL-1β were increased in the blood of first onset and acute relapse patients with schizophrenia." (PMID 29867314, 2018). "In chronic states, IL-6 was elevated in all three disorders, while IL-1β and sIL-2R were elevated in schizophrenia and bipolar disorder." (PMID 30766494, 2018). "For reason of the disease state, illness duration, medication, the timing of the assays and so on, the reports on levels of TNF-α and IL-1β in schizophrenia have been inconsistent." (PMID 29867314, 2018).
schizophrenia (continued). "Like IL1B, IL-1RN is located within the 2q13 chromosomal region for which significant evidence of linkage to schizophrenia has been found." (PMID 29464121, 2017). "According to the Australian group there can be a subtype of schizophrenia including patients displaying poor verbal fluency and reduced Broca’s area volume, in whom the IL-1β mRNA cytokine level is elevated." (PMID 26649857, 2017). "Using quantitative RT-PCR, we measured five cytokine mRNAs (IL-1β, IL-2 IL-6, IL-8 and IL-18) from peripheral blood of healthy controls and of people with schizophrenia or schizoaffective disorder (n = 165)." (PMID 28923068, 2017). "STRING analysis highlighted first-order protein interactions among IL12RB1 and IL12B, IL1B, IL6, and IL12A, all of which have previously been associated with schizophrenia." (PMID 27746755, 2016). "We also found that SFG volume was significantly negatively correlated with IL-1β mRNA levels in the schizophrenia group only (r=−0.563, P<0.01)." (PMID 27959331, 2016). "Mounting evidence indicates that in other neuropsychiatric conditions such as schizophrenia, inflammatory cytokines such as IL-1β and IL-6 have a role in onset and progress of neuropsychiatric symptoms." (PMID 25344730, 2014). "A recent genetic neuroimaging study detected the effect of the IL1B gene on frontal cortex function in schizophrenia." (PMID 23199001, 2012). "Future studies are warranted to replicate the present findings and to reveal the functional role of IL-1β gene in pathophysiology of schizophrenia." (PMID 21843369, 2011). "Findings of the present study provide further support for the role of IL-1β in the etiology of schizophrenia." (PMID 21843369, 2011). "The results of the present study provide further support for the role of IL-1β in the etiology of schizophrenia." (PMID 21843369, 2011). "Although no specific NLRP3 or IL1B gene variants have been directly associated with schizophrenia, autism, or depression, polymorphisms in these genes have been implicated in broader neuroinflammatory processes." (PMID 40713568, 2025). "Furthermore, a positive correlation between the total PANSS score and increased concentrations of IL-1β, sIL-2R, IL-13, IL-6, and IL-17 in chronic patients with schizophrenia was found." (PMID 40364201, 2025). "On the other hand, the expression of IL1-β was increased in human pluripotent cells derived from schizophrenic patients and later differentiated into neurons, as well as in the peripheral blood of patients diagnosed with schizophrenia." (PMID 41010622, 2025). "Additionally, increased concentrations of IL-1β, IL-6, IL-10, IL-17, and sIL-2, and a reduction in TNF-α are associated with more severe positive symptoms of schizophrenia." (PMID 40364201, 2025). "Additionally, Spearman’s analysis demonstrated that HERV-W env positively correlated with CASP1 (r = 0.7156), GSDMD (r = 0.7690), and IL1B (r = 0.6172) in the blood of schizophrenia patients." (PMID 39859234, 2025). "What is more, serum levels of IL-1β were significantly higher in UHR individuals for schizophrenia than in healthy individuals, suggesting that IL-1β may be a specific biomarker for UHR." (PMID 39858450, 2025). "This suggests that increased IL-1β in patients with schizophrenia may be responsible, not only for activation and maintaining an inflammatory state underlying the illness, but also for resistance to antipsychotics." (PMID 40364201, 2025). "Viral recognition by microglial Toll-like receptors (TLR2, TLR3, TLR9) triggers robust neuroinflammatory responses characterised by elevated key pro-inflammatory mediators such as IL-6, TNF-α, and IL-1β, patterns consistently observed in patients with schizophrenia." (PMID 40806558, 2025). "However, some reports, including a meta-analysis, demonstrated an increased IL-1β concentrations in patients suffering from schizophrenia, which was normalized under the influence of antipsychotic treatment." (PMID 41010622, 2025).
schizophrenia (continued). "Moreover, our clinical data revealed that the levels of CASP1, GSDMD, and IL1B in the blood of schizophrenia patients were significantly higher than those in healthy controls, consistent with the prediction from bioinformatics analysis of GSE25673." (PMID 39859234, 2025). "Notably, after 4 weeks of treatment with the neuroleptic risperidone, the serum levels of IL-1β in schizophrenia patients decreased significantly." (PMID 39766497, 2024). "An early study found that IL-1β, IL-6 and TNF-α could inhibit cortical neuronal dendritic development and possibly increase the risk of schizophrenia." (PMID 39831058, 2024). "The secretion and maturation of pro-inflammatory cytokines, such as IL1b and TNFa, in schizophrenia (SCZ) may be facilitated by MMP-9." (PMID 38254696, 2024). "Schizophrenia studies have found higher IL-6 levels in the CSF than in the blood and lower IL-1β CSF levels compared to those in the blood, as well as lower levels of IL-1β, IL-6, and TNF-α and higher IL-8 levels in the CSF than in the blood of MDD subjects." (PMID 37510730, 2023). "Serum IL-1β and IL-16 levels were different between patients with schizophrenia and healthy people." (PMID 37270510, 2023). "Therefore, the relationship between IL-1β and the pathological mechanism of schizophrenia deserves further exploration." (PMID 37946206, 2023). "The binary logistic regression analysis was used to explore whether serum IL-1β and IL-16 levels could relate to the onset of schizophrenia." (PMID 37270510, 2023). "Furthermore, the relationship between miR-3653-3p/NLRP3/caspase 1/IL-1β and the pathogenesis of schizophrenia was further verified by in vitro and in vivo experiments." (PMID 37946206, 2023). "A study of patients with schizophrenia reported that IL-1B exposure led to decreased chemotactic effect on T cells, suggesting astrocyte-derived chemokine CCL20 may be the cause of neuroinflammation in psychotic illness." (PMID 36358439, 2022). "IL-1β, IL-22, G-CSF, IL-21, and IL-10 were significantly higher in schizophrenia than in controls." (PMID 36256663, 2022). "However, one cell surface receptor mRNA, TNFR2, was increased even in people with schizophrenia with ‘normal’ levels of IL-1β mRNA and CRP relative to low inflammation controls." (PMID 35027554, 2022). "While these results corroborate a role for IL-1β signalling in schizophrenia, it is likely that the effects of this cytokine on NPCs are limited due to the lack of other cell types (such as microglia) in the culture system used or occur at another this involves another developmental stage." (PMID 35716830, 2022). "Moreover, increased neurotoxicity caused by increased levels of toxic cytokines (e.g., IL-1β, IL-6, IL-8, TNF-α, and IFN-γ) and chemokines (e.g., CCL11, CCL2, CXCL8, and CXCL10) is significantly associated with the G-CoDe and the schizophrenia phenome." (PMID 36256663, 2022). "We hypothesised that cortical neural progenitor cells (NPCs) derived from patients with schizophrenia would respond differently to IFNγ or IL-1β exposure compared to those of healthy controls." (PMID 35716830, 2022). "Therefore, it is likely that elevated FcGR3A contributes to the pattern of increased levels of IL-1β, IL-6, and TNFα in the midbrain which can be used to define the high-inflammation biotype of schizophrenia." (PMID 35841099, 2022). "We hypothesise that NPCs derived from patients with schizophrenia will respond differently to IFNγ and IL-1β compared to cells from healthy donors." (PMID 35716830, 2022). "Furthermore, postmortem studies indicate increased mRNA levels of IL-1β and IL-6 in schizophrenia as well as in bipolar disorder patients." (PMID 33976392, 2021). "Indeed, increased cerebrospinal fluid (CSF) concentrations of interleukin (IL)-6 is found in chronic schizophrenia and increased CSF IL-1β in first-episode schizophrenia." (PMID 33976392, 2021).
schizophrenia (continued). "Furthermore, IL-1β, a cytokine inducing the kynurenine pathway, is shown to be markedly elevated in the CSF of first-episode patients with schizophrenia or bipolar disorder with psychotic episodes." (PMID 33976392, 2021). "Schizophrenia has also been shown to be associated with polymorphisms of numerous genes responsible for the synthesis of such cytokines as IL1A, IL1B, IL10 and IL6, which are genes for, respectively, IL-1α, IL-1β, IL-10 and IL-6." (PMID 34501305, 2021). "In addition, IL1B mRNA was increased in high inflammation schizophrenia compared to low inflammation groups (59–71%, p < 0.035) and increased in high compared to low inflammation bipolar disorder (81%, p = 0.02)." (PMID 34911938, 2021). "Moreover, studies of cerebrospinal fluid (CSF) have shown increased levels of pro-inflammatory markers in schizophrenia patients when compared with healthy controls, including IL-1β, IL-6 and S100B." (PMID 30355368, 2019). "Indeed, in schizophrenia, hippocampal volumes correlate directly with the pro-inflammatory cytokine interleukin-18, while pro-inflammatory IL-1β titres correlate indirectly with Broca’s area volume in a “pro-inflammatory” subgroup of patients." (PMID 29743584, 2019). "Patients with first episode of schizophrenia as well as its relapse were reported to have increased serum level of IL-6, tumor necrosis factor α, IL-1β, and interferon-γ and decreased serum concentration of anti-inflammatory interleukin-10 (IL-10) (Müller 2018)." (PMID 30178287, 2019). "Furthermore, elevated proinflammatory cytokines, e.g., IL-6 and IL-1β, are inversely related to cognition and frontal brain volume in chronically ill people with schizophrenia." (PMID 30364161, 2018). "Furthermore, psychotic symptoms were positively related to IL-1β levels in individuals with schizophrenia." (PMID 29803226, 2018). "Thirdly, we did not collect some important clinical information, such as smoking, BMI and other data, which may affect the TNF-α and IL-1β levels in schizophrenia patients." (PMID 29867314, 2018). "Few studies has explored the interaction between TNF-α and IL-1β in patients with schizophrenia." (PMID 29867314, 2018). "Both TNF-α and IL-1β were among the mostly reported cytokines in schizophrenia." (PMID 29867314, 2018). "Furthermore, in chronic patients, IL-6, soluble IL-2 receptor, and IL-1β were similarly elevated in schizophrenia and bipolar groups compared to controls." (PMID 29803226, 2018). "The magnitude of increase in IL-1β, IL-6, IL-8 and IL-10 mRNAs in people in the elevated inflammation biotype ranged from 100 to 220% of those in the non-elevated inflammatory biotype and was comparable between control and schizophrenia groups." (PMID 28923068, 2017). "On the contrary, increased IL-1β levels in the brain have been associated with schizophrenia but its levels are not significantly deregulated in autism brain samples." (PMID 28870209, 2017). "Single nucleotide polymorphisms have been analysed in many cytokines, in particular, those that are associated with altered levels in schizophrenia such as TNF-α, IL1-β, IL-6, IL-10, INF-γ, and in the genes encoding the immune system regulatory proteins CTLA-4 and CD28." (PMID 29317797, 2017). "A recent meta-analysis on the effect of anti-psychotic drugs on blood levels of cytokines in patients with schizophrenia found that haloperidol and clozapine treatment increases peripheral sIL-2R levels, but leads to decreases in IL-1β and IFN-Υ, and possibly increases in IL-12." (PMID 28870209, 2017). "However, gender differences have been reported in the association between schizophrenia and RELA gene encoding the major component of NF-κB, which is activated by IL-1β." (PMID 21843369, 2011). "Similarly, others observed unaltered IL-1β in patients known for schizophrenia." (PMID 41010622, 2025). "Thus, a decrease in IL-1β during treatment may be a marker of clinical improvement in schizophrenia." (PMID 41010622, 2025).